BMP6 (bone morphogenetic protein 6)
Diseases named in the same sentence as BMP6 in open-access papers (continued):
Sharing a sentence is not in itself a finding about the gene and the disease.
infection (10 papers, 2012 to 2023). The state of being infected such as from the introduction of a foreign agent such as serum, vaccine, antigenic substance or organism. "ZIKV suppressed BMP6 expression as well as the downstream signaling as evidenced by decreased phosphorylation of SMAD1/5 at the later stages of infection." (PMID 36713156, 2022). "Compared with the empty vector group (Ctrl-Sh), the expression of BMP6 in the BMP6-shRNA infection groups was reduced." (PMID 36532723, 2022). "Our study revealed that the infection with the active form of AMPK progressively reduced phosphorylation of Smad1/5 induced by BMP6, concomitant with elevation of Smad6." (PMID 33169942, 2020). "At 8 weeks post-infection, expression of BMP6, HAMP, FPN1, FTH1, NRF2, and LCN2 was significantly up-regulated, while HFE1 was significantly down-regulated by Fe-supplementation, compared to the placebo group." (PMID 31382404, 2019). "The level of BMP6 expression was found to be significantly increased following Ad‐BMP6 infection." (PMID 37313693, 2023). "It is likely that BMP6 suppression during the later stages of infection may be a virus-induced response to negatively impact the robustness of the interferon response, possibly another mechanism by which ZIKV antagonizes the IFN response." (PMID 36713156, 2022). "Next, to assess whether BMP6 affects ZIKV replication, SC were treated with BMP6 at the concentration of 60 and 100 ng/mL based on other studies for 24 h before infection and then replenished with fresh BMP6 every 24 h." (PMID 36713156, 2022). "Therefore, we next assessed the gene expression of two key BMPs (BMP2 and BMP6) at different time points after infection." (PMID 36713156, 2022). "Among the tested Fe-responsive genes, expression of HFE1, BMP6, and HMOX1 at 12 weeks, and HAMP at 16 weeks post-infection, was significantly up-regulated." (PMID 31382404, 2019). "Expression of BMP6 and FTH1 were up-regulated by Fe-supplementation at both, 4 and 8 weeks post-infection." (PMID 31382404, 2019). "Fe-supplementation resulted in a significant down-regulation of HFE3 (TFR2), HAMP, FPN1, and LCN2 while BMP6 and FTH1 were significantly up-regulated, compared to the placebo group, at 4 weeks post-infection." (PMID 31382404, 2019). "While ZIKV did not modulate the expression of TGF-β and Activin A, BMP6 signaling was suppressed at later stages of infection." (PMID 36713156, 2022). "In summary, our data indicate that the innate immune response to ZIKV in SC is induced through RIG-I and MDA5 pathways, and modulation of BMP6 and downstream signaling by ZIKV at later stages of infection may negatively modulate antiviral response and facilitate virus persistence in infected SC." (PMID 36713156, 2022).
adenocarcinoma (2 papers, 2009 to 2025). A common cancer characterized by the presence of malignant glandular cells. "Notably, Bmp6 (bone morphogenetic protein 6) was significantly −29.4-fold down regulated in adenocarcinoma when compared with transgenic cells and −35.2-fold down regulated in adenocarcinoma versus non-transgenic cells." (PMID 19812696, 2009). "Notably, Bmp6 was strongly down regulated in our transgenic adenocarcinoma model." (PMID 19812696, 2009).
inflammation (2 papers, 2013 to 2014). Aberrant reaction of the microcirculation characterized by movement of fluid and leukocytes from the blood into extravascular tissues. "The genes BMP6, CFB and MYLK have previously been associated with airway inflammation and hyperresponsiveness." (PMID 24475887, 2014).
neurodegenerative disease (1 paper, 2016). A disorder of the central nervous system characterized by gradual and progressive loss of neural tissue and neurologic function. "Our data also suggest a progressive imbalance of the Bmp6/Noggin ratio that may negatively affect proliferation, differentiation and activity of many cell types, and may be related to the pathophysiology of neurodegenerative diseases." (PMID 27545843, 2016).
vascular disorder (1 paper, 2006). A general term used to describe any disease affecting blood vessels]. "Furthermore, the ALK1-response genes endothelin (ET-1), heme oxygenase (HO-1) and BMP6 might also be involved in other vascular disorders." (PMID 16594992, 2006).
BMP6 also shares sentences with these, for which no sentence is quoted: multiple myeloma (5 papers); squamous cell carcinoma (3); ankylosing spondylitis (2); cardiovascular disease (2); cervical cancer (2); craniosynostosis (2); dyslipidemia (2); Hypertension (2); ocular melanoma (2); osteonecrosis (2); schizophrenia (2); septic shock (2); systemic inflammatory response syndrome (2); allergic rhinitis (1); amoebiasis (1); bacterial infection (1); basal cell carcinoma (1); benign tumors (1); brachydactyly (1); breast (1); calcification (1); carotid atherosclerosis (1); Cerebral ischemia (1); Chagas disease (1); childhood asthma (1); cholangitis (1); chondrodysplasia (1); chronic kidney disease (1); colon adenocarcinoma (1); dermatitis (1).
A further 53 diseases each share a sentence with BMP6 in 1 paper.